CD44 (CD44 molecule (IN blood group))
Diseases named in the same sentence as CD44 in open-access papers (continued):
Sharing a sentence is not in itself a finding about the gene and the disease.
glioma (375 papers, 2007 to 2025). A benign or malignant brain and spinal cord tumor that arises from glial cells (astrocytes, oligodendrocytes, ependymal cells). "In contrast, the expression levels of the hyaluronic acid receptor Cd44 and the gene encoding hypoxia-inducible factor 2 alpha (HIF2a), Epas1, were lower in rat glioma 101.8 relative to healthy brain tissue." (PMID 41009560, 2025). "CD44 (alias CSPG8) is a glycoprotein receptor that has been linked to glioma WHO grade, GBM cell stemness, invasion, poor prognosis and the mesenchymal subtype." (PMID 38414005, 2024). "Consistent with the present findings, CD44 expression is associated with poor prognostic outcome of glioma, BLCA, STAD, HNSCC, KIRC, LIHC, PAAD,MESO,and THYM." (PMID 38590654, 2024). "According to our exploration of the distinct genomic alternations of CD44, we found a negative association between the events of somatic mutations and CD44 expression, which indicated that CD44 expression was correlated with the aggressive glioma process." (PMID 36776876, 2023). "CD44 has also been identified as a novel biomarker for M2 tumor-associated macrophages in glioma patients with a poor prognosis." (PMID 38066643, 2023). "We implied a prognostic nomogram model developed by CD44 expression and clinicopathological risk factors to test its prediction in the clinical prognosis of gliomas." (PMID 36776876, 2023). "CD44 (Cluster of Differentiation 44) is a transmembrane protein, overexpressed in multiple cancer types, including gliomas, and implicated in cell motility, proliferation and angiogenesis." (PMID 35992852, 2022). "While a variant of CD44 expression is detected in metastatic tumors, the cleaved CD44 is detected in 60% of gliomas, and its expression correlates with the glioma grade." (PMID 35053605, 2022). "A trial showed that depletion of CD44 make glioblastoma cells susceptible to chemotherapy and overexpression of CD44 make more colonies of glioma cells even after chemotherapeutic dose." (PMID 36185622, 2022). "Analysis on glioma-associated myeloid cells (GAMs) isolated from control and cKO mice showed an average of 80% decrease in CD44 mRNA." (PMID 35992852, 2022). "Recent studies have suggested that high expression of CD44 in glioma cells is associated with the mesenchymal transition, increased recruitment of macrophages and reduced survival time in glioma patients." (PMID 36555253, 2022). "Altogether, our mRNA analysis in vitro and in vivo show that myeloid-cKO of CD44 severely hampers MMP9 upregulation in glioma-associated myeloid cells, and additionally affects levels of the pro-inflammatory cytokines." (PMID 35992852, 2022). "M2 TAM accelerating tumorigenicity is one of the underlying reasons why CD44 can be the convincing prognostic biomarker for glioma." (PMID 35187044, 2021). "We support the conclusion that high mRNA expression of CD44 is associated with a poor prognosis of grade II–III gliomas." (PMID 33030522, 2020). "The result (HR = 1.71, 95% confidence interval = 1.33–2.21) suggested that high expression of CD44 is associated with a poor prognosis in grade II–III gliomas." (PMID 33030522, 2020). "Loss of EMP3:CD44 interaction has also been reported in glioma, where ablation of EMP3 attenuates proliferation." (PMID 32678083, 2020). "In contrast to GAPDH (negative control), selective association with GFP-MSI1 was also determined for the CD44 mRNA, supporting the conserved association of MSI1 and the CD44 mRNA in glioma-derived cell models." (PMID 33291443, 2020). "CD44, a hall marker in glioma, has been reported to be associated with epithelial-mesenchymal transition (EMT) and angiogenesis, which play important roles in glioma progression." (PMID 31528214, 2019). "In general, increased HA expression is associated with an increase in motility and migration of glioma, probably via a CD44 or RHAMM induced activation of Rho GTPases, such as Rac1 or Cdc42." (PMID 31003495, 2019).
glioma (continued). "In glioma cell lines, genetic inhibition of ERK5 decreases HGF-induced cell migration and invasiveness in vitro and reduces the expression of the mesenchymal marker N-cadherin and CD44, which are associated with glioma invasiveness." (PMID 30901834, 2019). "The HA–CD44 interaction and CD44 shedding from the cell surface were found to be associated with glioma cell motility, migration, and infiltration into the normal brain parenchyma." (PMID 30304861, 2018). "In murine model of PDGF-induced glioma osteopontin secreted by glioma-associated astrocytes enhanced the cancer stem cell phenotype through interactions with CD44." (PMID 28030801, 2017). "CD44 expression is increased in GBM compared to low-grade gliomas and high levels of CD44 are associated with worse survival of GBM patients." (PMID 28380429, 2017). "Recently, tTG has also been implicated in the survival and proliferation of CD44+ glioma stem cells (GSCs), as well as the survival, migration, invasion, and self-renewal of epidermal squamous cell carcinoma stem cells." (PMID 28423611, 2017). "Recently, CD44 has also been found to be increased in glioma cells compared to healthy astrocytes, and has been implicated to directly impact glioma invasion." (PMID 27120809, 2016). "Previous studies demonstrated that cancer cells typically produce several variant forms of CD44 in addition to the standard CD44, whereas some tumor types, e.g., gliomas, produce mainly the standard form." (PMID 25909172, 2015). "CD44/CD155-silencing significantly inhibited the invasive phenotype of glioma cells associated with decreased expression of some of the key mediators of invasion, particularly F-actin, integrins, Rac 1/2/3, RhoA and Cdc42." (PMID 22363471, 2012). "CD44 has long been associated with glioma invasion while, more recently, CD155 has been implicated in playing a similar role." (PMID 22363471, 2012). "Further study on the effects of ANXA5 may contribute to understanding the potential mechanism associated with MAPK/CD44 pathway in glioma progression." (PMID 40607003, 2025). "CD44 overexpression is associated with poor prognosis in grade II/III gliomas." (PMID 39619148, 2024). "CD44 has also been implicated in mediating glioma cell migration." (PMID 38737451, 2024). "Moreover, high expression levels of CD44 were closely correlated to the CL and MS molecular subtypes, which indicated its potential to be a sensitive glioma diagnostic biomarker." (PMID 36776876, 2023). "In low-grade gliomas, elevated CD44 is associated with poor prognosis." (PMID 36835465, 2023). "Besides, CD44 was recently demonstrated to be associated with the M2-polarization of tumor-associated macrophages and immunosuppression of glioma." (PMID 36776876, 2023). "Interestingly, the IDH-mutated gliomas, linked with better clinical outcomes, were associated with a lower CD44 level in pan-gliomas and GBM cases." (PMID 36776876, 2023). "The results showed that CD44 expression was closely associated with glioma occurrence." (PMID 36776876, 2023). "These shows that a higher CD44 expression is associated with a higher malignancy in glioma." (PMID 35187044, 2021). "We have previously shown that CD44 is the CCL5 receptor on Nf1-deficient high-grade glioma cells." (PMID 32358581, 2020). "However, CD44 in the context of glioma is also associated with adhesion, migration, and cancer cell proliferation, thereby favoring therapy resistance." (PMID 31936544, 2020). "Further studies are needed to determine the key signaling pathways underlying the role of CD44 in glioma, which may be helpful to develop the CD44-based target therapy for patients with glioma." (PMID 32232385, 2020). "Since the sample sizes of such studies are limited, they may be too underpowered to show a significant association between tumor CD44 levels and the prognosis in glioma patients." (PMID 32232385, 2020).
glioma (continued). "Furthermore, they showed that in a subset of the PN/CIMP− glioma stem cells, mesenchymal differentiation was associated with enrichment of CD44-expressing subpopulations and with poor radiation response." (PMID 30279357, 2018). "Furthermore, CD44 expression was significantly associated with the glioma grade; 5% in LGG versus 46% in GBMs." (PMID 28279210, 2017). "CD44 is a cell-surface marker associated with tumor progression and treatment resistance in glioma." (PMID 27527869, 2017). "As CD44 is associated with glioma stem cells and recent studies indicate a reciprocal link between CD44 and ZEB1 we tested whether ZEB1 may be a substitute marker for CD44." (PMID 28445977, 2017). "Moreover, HMGA2 expression is positively correlated with expressions of STAT3 and C/EBPβ, two essential transcription factors that promote mesenchymal phenotypes in GBMs; as well as that of CD44, another hallmark of glioma invasiveness." (PMID 27259253, 2016). "CD44, a glycoprotein transmembrane receptor, is a marker of stem cells from a variety of normal and neoplastic tissues and is associated with treatment resistance of glioma." (PMID 25605243, 2015). "Our previous studies have linked local invasion of glioma cells to elevated level of CD44." (PMID 22363471, 2012). "Another study with glioma and pancreatic cancer cells showed that the use of methyl‐β‐cyclodextrin to deplete cholesterol in cell membranes and destroy lipid rafts resulted in increased extracellular lipid distribution of CD44 and promoted ADAM‐10‐mediated CD44‐associated tumour metastasis." (PMID 34939255, 2022). "Moreover, one of the studies even showed that higher tumor expression of CD44 may be associated with improved OS in glioma patients." (PMID 32232385, 2020). "However, the association between CD44 and poor OS remains inconsistent in glioma." (PMID 32232385, 2020). "In GBM, high CD44 expression has previously been shown to be a biomarker for glioma stem cells and indicates cells that are highly invasive." (PMID 41463154, 2025). "The transmembrane glycoprotein CD44 plays a significant role in glioma pathogenesis, mediating both matrix adhesion and activation of signaling pathways that control invasion." (PMID 41304780, 2025). "TCGA database analysis further revealed a strong positive correlation between NFE2L2 (the gene encoding NRF2) and CD44, TNFRSF1A, and ANXA1 expression in glioma tissues." (PMID 40583858, 2025). "CD44 has been reported to be expressed by several cell types in the glioma TME, including immune cell subsets and glioma stem cells." (PMID 39880824, 2025). "In another study, a triple-membrane hybrid composed of erythrocytes, U251 glioma cells, and macrophages integrated key membrane markers from each source—CD47 for immune evasion, CD44 for glioma targeting and BBB transport, and CD86 for immune modulation." (PMID 40624508, 2025). "An interaction between SPP1 and CD44 has previously been postulated for glioma, yet here we show an unexplored role of these molecules in conveying communication between GTCs, microglial cells and T cells." (PMID 39880824, 2025). "Their study demonstrated that lactate-stimulated glioma cells exhibited enhanced CD44 expression and exosome secretion, which in turn promoted tumor cell migration and angiogenesis." (PMID 40801693, 2025). "A marked upregulation of CD44 expression has been detected in tumors originating from astrocytes (gliomas) and oligodendrocytes (oligodendrogliomas), in line with the widely described expression of CD44 in neoplasms." (PMID 40943148, 2025). "More importantly, ANXA5 was positively correlated with Cluster of differentiation-44 (CD44) according to the Chinese Glioma Genome Atlas (CGGA) database." (PMID 40607003, 2025). "CD44 is a ubiquitously expressed molecule that is extensively described as a marker for IDHwt and IDHmt glioma as well as for reactive astrogliosis." (PMID 39880824, 2025).
glioma (continued). "Microglia/macrophages within the glioma microenvironment also express high levels of CD44 correlated with tumor progression in humans." (PMID 41282250, 2025). "At the cellular level, the results showed that CD62P on the surface of PMs facilitated the targeting of Dox@PNGs to glioma cells by specifically binding to CD44 on glioma cell surfaces." (PMID 39911305, 2025). "Meanwhile, we found that the expression of CD44 was monitored by ANXA5, and ANXA5 promoted the migration and proliferation of glioma cells via the MAPK/CD44 pathway." (PMID 40607003, 2025). "Epas1 expression is correlated with the expression of another important marker of glioma stem cells (GSCs), the hyaluronic acid receptor gene Cd44." (PMID 41009560, 2025). "In a functional context, inhibiting GALNT2 disrupts the growth, self-renewal, and aggressive behavior of glioma stem-like cells, primarily by downregulating CD44 expression." (PMID 38596689, 2024). "PTX-encapsulated micelles were exocytosed into the brain and subsequently entered glioma cells via receptor-mediated endocytosis utilizing CD44." (PMID 38399342, 2024). "Brain tumors such as glioma highly express CHI3L1 by interacting with CD44 on the surface of glioma stem cells (GSCs) that result in activating the Akt and β-catenin signaling cascades." (PMID 38667293, 2024). "Higher PTK7 expression was consistent with higher CD44 expression in the mesenchyma-like glioma subtype." (PMID 39474113, 2024). "In MAN1C1-expressing glioma cells, the presence of highly glycosylated receptors, such as CD44 and integrins (ITGB1, ITGAV, ITGA8, ITGAB1) facilitates this interaction." (PMID 39333557, 2024). "Glioma cells can enhance their expression of CD44, the primary surface receptor for HA, which also binds to matrix metalloproteinase 9 (MMP9) present in the ECM." (PMID 39033204, 2024). "Silencing HAS3 expression or blocking CD44 slowing down glioma cell proliferation, through the inhibition of autophagy and cell cycle arrest in G1 phase." (PMID 38969910, 2024). "Mechanistically, PTK7 knockdown attenuates tumor cell proliferation and impairs tumorigenic potential in CD44-high glioma cell lines." (PMID 39474113, 2024). "OPN is reported to enhance the radiation resistance by maintaining stemness in the adjacent cells through activation of CD44 in glioma." (PMID 39062100, 2024). "Following the knockdown of PLAUR in glioma cells, the decreased expression of CD44 and vimentin was detected by Western blotting, while the overexpression of PLAUR via a plasmid was shown to elevate the protein level." (PMID 38398231, 2024). "A previous study showed that PTK7 expression was significantly positively correlated with the expression of CD44, a biomarker for the mesenchyma-like glioma subtype." (PMID 39474113, 2024). "Recent studies demonstrated that knockdown of SPRY2 enhances CD44 in cancer-associated fibroblasts, whereas knockdown of SPRY1 reduces stemness of patient-derived glioma stem cell spheres." (PMID 39682716, 2024). "The research of Gu and colleagues showed that sEVs-EpCAM promoted glioma metastasis via targeting CD44 signaling molecules which are on the surface of glioma cells." (PMID 38951882, 2024). "For example, in gliomas, CD44 modulates MET signaling, primarily affecting cell proliferation without significantly altering survival pathways." (PMID 39769452, 2024). "As a result, patients with high level of both SPP1 and CD44 had an increased macrophages infiltration and a poor prognosis in glioma." (PMID 38346944, 2024). "These GL261 results are consistent with findings showing human glioma stem cells treated with the SMC birinapant for 7 days lead to increased expression of CD44." (PMID 39147758, 2024). "ELF4 is elevated in high grade gliomas, particularly in glioma and neuronal stem cell markers, including CD44, CD36, CD15, CD70, S100A4, and ALDH1A3." (PMID 38539424, 2024).
glioma (continued). "In this context, functioning as a ubiquitous protein binding component of the extracellular environment, CD44 is overexpressed in various tumors, including gliomas." (PMID 38473812, 2024). "In this regard, a promising cancer treatment target is CD44, a transmembrane glycoprotein overexpressed in several solid tumors such as melanoma, non-Hodgkin's lymphomas, gliomas, or meningiomas, all of them also present in the eye." (PMID 38239894, 2024). "effectively knocked out CD44 within myeloid cells, endothelial cells and astrocytes in mice and confirmed the role of CD44 expression in myeloid cells in promoting glioma invasion." (PMID 38590654, 2024). "According to our findings by a large-scale bioinformatic analysis, we investigated the features and patterns of CD44 among gliomas." (PMID 36776876, 2023). "To detect the intra-tumor distribution of CD44 expression in glioma tissues, we examined CD44 expression levels in disparate structures." (PMID 36776876, 2023). "A previous scRNA-seq analysis revealed SPP1/CD44-mediated crosstalk between macrophages and cancer cells in glioma." (PMID 36776876, 2023). "The hyaluronic acid acts as a biomimetic ligand to CD44, selectively targeting CD44 overexpressing glioma cells thereby improving anti-tumor efficacy of doxorubicin." (PMID 37483515, 2023). "Collectively, these data show that human gliomas with high CD44 expression display histological and molecular features of aggressive and TMZ-resistant tumors." (PMID 36989359, 2023). "The expression profiles of CD133, CD44, Nestin, SOX2, Nanog, ALDH1A3 and OCT4, which are associated with glioma stem cell (GSC) signatures, were visualized in a heatmap." (PMID 36755314, 2023). "A recent single‐cell study of glioma also revealed that SPP1/CD44‐mediated intercellular interaction between macrophages and cancer cells plays a critical role in glioma progression." (PMID 37194413, 2023). "Further study showed that the miR-21/SP1/DNMT1 positive feedback loop in MSCs triggered by glioma exosomal CD44 upregulated MSC exosomal miR-21 expression, amplifying the glioma exosomal immunosuppressive signal." (PMID 37481646, 2023). "Glioma stem-like cells expressing high levels of CD44 are highly invasive and are required to change to less invasive, more proliferative types to generate a recurrent tumor." (PMID 37835592, 2023). "All established early-passage glioma cell cultures were characterized by the presence of a large amount of CD44+ cells; 7194 cells from the 8803 totally investigated were CD44+." (PMID 36835465, 2023). "Previous research has revealed a critical role of macrophage‐mediated SPP1/CD44 signaling in glioma progression." (PMID 37194413, 2023). "Studies had shown that SPP1/CD44 signaling in the perivascular niche promotes the stem cell-like properties of glioma cells and that increased SPP1 expression induces GBM-associated macrophage infiltration." (PMID 37583898, 2023). "A retrospective analysis of clinical reports of gliomas confirmed that CD44 expression was significantly predictive of shorter overall survival in patients with WHO grade II and III gliomas but not in patients with glioblastomas." (PMID 38275375, 2023). "Based on the TCGA dataset, GBM and pan-gliomas of CL and MS subtypes had significantly higher expression levels of CD44 compared to subtypes of PN." (PMID 36776876, 2023). "According to the immunohistochemical analysis on tumor sections, CD44+ cells range from 60% to 90% of the population in glioma." (PMID 36835465, 2023). "In glioma cells, lactate-stimulated malignant glioma exosomes enhance the migratory and angiogenic effects of tumor cells through CD44, and there is a positive correlation between the malignant behavior of gliomas and their exosomal CD44 levels." (PMID 36964570, 2023). "CD44 expression level strongly correlates with stromal and immune cells, mainly infiltrating the glioma microenvironment by single-cell sequencing analysis." (PMID 36776876, 2023).